NRP1 (neuropilin 1)
Diseases named in the same sentence as NRP1 in open-access papers (continued):
Sharing a sentence is not in itself a finding about the gene and the disease.
tumor (continued). "Nrp1 protein was expressed in tumor cells as well as in vascular endothelial cells comprising intratumoral blood vessels." (PMID 28938007, 2017). "All of the initially published data examining the role of NRP1 in cancers showed that NRP1 stimulated tumor growth." (PMID 29018205, 2017). "NRP1 is expressed on TAMs and is crucial for their migration to the hypoxic niche of the tumor in response to Sema3A." (PMID 29067024, 2017). "This leads to differential Nrp1-dependent TGFβ receptor signaling in tumor cells versus endothelial cells and possibly other stromal cells." (PMID 28938007, 2017). "Immunofluoescent staining in tumor section suggested a sporadic pattern of Nrp1+ cells in MMTV-Wnt1 tumor epithelial compartment." (PMID 28887477, 2017). "In the tumor context, Treg-restricted Neuropilin-1 deletion can revert antitumor responses based on more than one pathways: first, Neuropilin-1 directly enforces Treg stability and function in the tumor microenvironment." (PMID 29225597, 2017). "The RGD peptide then would combine with the peptide ligand for neuropilin-1, giving rise to selective tumor vascular targeting and facilitating the penetration of imaging agents into the tumor." (PMID 28416757, 2017). "In summary, our study provides some insight regarding the pro-tumor and anti-tumor functioning of NRP1 in different cancer types." (PMID 29018205, 2017). "RNAi-mediated NRP1 silencing unexpectedly leads to enhanced tumor growth, suggesting that Nrp1 suppresses proliferation in GBM cells in vivo." (PMID 28938007, 2017). "After proteolytic cleavage, iRGD gains affinity toward neuropilin-1 (NRP-1) where it mediates further tumor tissue penetration." (PMID 28993773, 2017). "We show that both plasma and tumor tissue NRP-1 is upregulated in patients with advanced diseased nodes and in metastatic breast cancer." (PMID 28607365, 2017). "When injected into tumors, these NRP1-expressing monocytes promoted tumor vasculature normalization." (PMID 29067024, 2017). "In comparison to U87-bevS tumors, human Nrp1 protein was significantly down regulated in all four U87-bevR tumor xenografts, as revealed by immunoblotting lysates with a human-specific anti-Nrp1 antibody." (PMID 28938007, 2017). "In contrast, in all three recurrent GBM samples (bevacizumab-resistant) we detected a striking reduction in Nrp1 protein expression in tumor cells as well as in many intratumoral blood vessels." (PMID 28938007, 2017). "Inhibition of NRP1 expression, however, has differing pro-tumor vs. anti-tumor effects, depending on the cancer types." (PMID 29018205, 2017). "TGF-β signaling seems to be less of a requirement for the suppression of Th1 and Th17 cell-mediated inflammation and its facilitation of tumor growth through increasing tumor-derived Nrp-1+ Treg cells." (PMID 27075020, 2016). "In this experiment, tumor tissues from the mice treated with the anti-Nrp-1 antibody exhibited fewer Ki-67-positive cells." (PMID 27075020, 2016). "This part of the study demonstrated that blocking NRP1 in triple-negative breast tumors significantly blocks tumor growth in all treated mice." (PMID 27351129, 2016). "The neutralization of Nrp-1 in the IL-10−/− or WT B16/F10 mice resulted in elevated tumor-derived CD8a+ or IFN-γ protein expression in CD8+ T cells." (PMID 27075020, 2016). "In our study, we demonstrated that the NDGA impairs tumor cell motility through suppressing NRP1, revealing a novel functional target of NDGA." (PMID 27863391, 2016). "Our previous studies demonstrated that LKB1 promotes NRP-1 degradation and inhibits tumor angiogenesis and growth." (PMID 26701889, 2016). "When administrating the peptide to the mice before grafting tumor cells, the number of metastatic events dropped suggesting that the seeding capacity of the cells is affected when blocking NRP1 in the microenvironment." (PMID 27351129, 2016).
tumor (continued). "Neuropilin 1 (Nrp1) is a transmembrane receptor that in mice both amplifies pro-angiogenic signaling in the tumor microenvironment and affects behavior of innate immune cells." (PMID 26755653, 2016). "NRP1 is known to facilitate the interaction between tumor cells and microenvironment by affecting FN assembly." (PMID 27863391, 2016). "In many types of cancer including breast, prostate, pancreatic, colon and kidney cancer, NRP1 can be found overexpressed and the abnormal expression pattern usually correlates with tumor aggressiveness, metastasis and poor prognosis." (PMID 27863391, 2016). "In contrast, tumor progression is paralleled by a reduction in Nrp-1-producing Tregs controlled by the IL-10 and TGF-β1 levels." (PMID 27075020, 2016). "NRP1 also facilitates fibronectin fibril assembly in the tumour microenvironment, promoting desmoplasia." (PMID 26923176, 2016). "It is reported that NRP1 promotes integrin α5β1-dependent fibronectin fibrils assembly, matrix stiffness and tumor growth." (PMID 27863391, 2016). "Antigen-stimulated Tregs secrete TGF-β, thereby enabling tumor growth; this growth is dampened by Nrp-1+ Tregs concomitant with the presence of IL-10." (PMID 27075020, 2016). "We show that tumor tissue can secrete Nrp-1 and VEGF to support its growth, and their production closely parallels the co-expression levels of IL-10 and TGF-β." (PMID 27075020, 2016). "NRP-1 depletion suppressed tumorigenesis, tumor growth and lung metastasis by inhibiting cell proliferation and tumor angiogenesis in situ." (PMID 26795388, 2016). "To directly link the preliminary in vitro knockdown studies with the pathobiology of tumor fibrosis, we further tested the effects of NRP-1 silencing in a clinically relevant orthotopic model of PDAC in athymic rats." (PMID 27542226, 2016). "Collectively, our data indicate that Nrp-1 deficiency in CD4+Foxp3+ regulatory T cells in combination with increased Th1 and Th17 cell immunity results in decreased tumor growth, although elevated expression of Tregs is detected in IL-10−/− B16/F10 mice." (PMID 27075020, 2016). "Aberrant NRP-1 expression has been described in human malignancies with links to several tumor phenotypes, including growth, migration, invasion, and angiogenesis." (PMID 26701889, 2016). "We conclude that Nrp-1 is highly expressed by Tregs that control Foxp3+ Treg migration into the tumor, and this process is highly dependent on tumor-derived IL-10." (PMID 27075020, 2016). "Third and most importantly, our data demonstrate that IL-10 deficiency impairs Treg-derived Nrp-1 functions to promote Th1 and Th17 immunity, suggesting that Nrp-1 is a critical molecule in tumor pathogenesis." (PMID 27075020, 2016). "This study defines a previously unrecognized role of NRP-1 in regulating TGFβ1-induced EndMT and fibrosis, and advocates NRP-1 as a therapeutic target to reduce tumor fibrosis and PDAC progression." (PMID 27542226, 2016). "These promising human data prompted us to specifically focus further on the role of NRP-1 in EndMT-induced tumor fibrosis." (PMID 27542226, 2016). "Aside from modulating NRP1 function, CendR peptides have been proposed as useful agents for delivering cargo into endothelial and tumour cells, as they can be chemically coupled to other molecules and undergo NRP1-mediated endocytosis." (PMID 26923176, 2016). "Taken together, our results indicate the potential application value of NDGA in cancer therapies targeting NRP1 in selected tumor types with NRP1 overexpression." (PMID 27863391, 2016). "Small molecule inhibitor, specific antibody or short peptide targeting NRP1 have been shown to suppress tumor growth and metastasis." (PMID 27863391, 2016). "Both TDLN and tumor-derived CD4+IFN-γ+ (Th1) cells were significantly elevated in IL-10−/− B16/F10 mice treated with the anti-Nrp-1 antibody." (PMID 27075020, 2016).
tumor (continued). "The mean density of tumor blood vessels in the blocked Nrp-1-treated tumors was clearly lower than the mean density in the control group." (PMID 27075020, 2016). "Using this model, we clearly demonstrated that increased expression of NRP1-Δ7 inhibits tumor growth and intratumoral angiogenesis." (PMID 27798666, 2016). "Inhibition of TGF-β or IL-10 resulted in decreased Nrp-1 expression in tumor tissue and reduced tumor-derived VEGF." (PMID 27075020, 2016). "Because NRP1 interacts with several growth factors and other ligands, its blockade can alter responses in tumour-cell assays." (PMID 27486976, 2016). "Unsurprisingly, NRP-1 is highly expressed in various human neoplasm and contribute to tumor growth, neovascularization and metastasis." (PMID 26701889, 2016). "Results show that NRP1 expression level in tumor tissues are lower in NDGA treated groups, consistent with our in vitro results." (PMID 27863391, 2016). "Surprisingly, the Nrp-1-expressing CD4+ T cells obtained from the tumor and TDLN were strongly up-regulated in IL10−/− B16/F10 mice, with the exception of the spleen." (PMID 27075020, 2016). "Our data showed that TGF-β increased intratumoral Nrp-1 expression, thereby supporting tumor growth." (PMID 27075020, 2016). "Together, these results indicate that TU17:MTD and TU17-2:MTD target, penetrate, and kill the tumor cells by targeting to NRP-1 on tumor cells." (PMID 27083053, 2016). "As a co-receptor of VEGF, NRP1 is highly expressed in vascular endothelial cells and is critical in the regulation of tumor angiogenesis." (PMID 27863391, 2016). "In in vivo cancer models, NRP1 has also been demonstrated to be critical in promoting tumor metastasis." (PMID 27863391, 2016). "The impairment of tumor growth after treatment with anti-Nrp-1 confirms our finding that IL-10 plays a central role in this process." (PMID 27075020, 2016). "Treatment of the IL-10−/− B16/F10 mice with anti-Nrp-1 significantly reduced the tumor volumes in tumor-bearing mice." (PMID 27075020, 2016). "Nrp-1 is a high-affinity receptor for TGF-β1 on the membrane of tumor cells and can activate the latent form of TGF-β1, which is referred to as the “latency-associated peptide” (LAP)–TGF-β1." (PMID 27075020, 2016). "Nevertheless, the mechanism by which SEMA3A modulates the expression pattern and activity of NRP1 and, consequently, the phenotype of the tumor requires further study." (PMID 26755661, 2016). "Using subcutaneous xenograft model we confirmed that NDGA suppresses NRP1 expression in tumor tissue." (PMID 27863391, 2016). "Nrp-1 is highly expressed by Foxp3+ Tregs, which appear to regulate immunological anti-tumor control mechanisms in response to tumor-derived VEGF39." (PMID 27075020, 2016). "Even though tumour studies had shown that the NRP1 cytoplasmic domain is important for ABL1 function in fibronectin fibrillogenesis, the NRP1 cytoplasmic domain is not required for angiogenesis." (PMID 26923176, 2016). "In recent years, various approaches targeting NRP1 have been proved to execute anti-tumor effect in both cultured cells and animal models, indicating NRP1 as a promising drug target in anti-cancer therapy." (PMID 27863391, 2016). "The tumor-homing motif of TU17:MTD has a “RPARPAR” sequence containing the C-end rule (CendR) element that has known to bind to neuropilin-1 (NRP-1), although the “RPARPAR” sequence is located at the N-terminus of the MTD rather than at the C-terminus." (PMID 27083053, 2016). "In particular, NRP1's ability to modulate vascular responses in tumour growth has sparked much interest in manipulating its function." (PMID 26923176, 2016). "Neuropilin-1 (NRP-1) has emerged as an important driver of tumor-promoting phenotypes of human malignancies." (PMID 26701889, 2016).
tumor (continued). "Initially implicated in the development of the nervous system, growing evidence suggests a significant role for neuropilin-1 (NRP-1) in cancer where it appears to be involved in angiogenesis and other aspects of tumor progression." (PMID 27542226, 2016). "Given well-established pleiotropic tumor-promoting functions, and canonical pro-angiogenic roles that support survival of malignant cells, neuropilin-1 (NRP-1) was an attractive target to investigate." (PMID 26701889, 2016). "The tumor-penetrating ability of iRGD mainly depends on the molecules ανβ3, ανβ5 and NRP-1 overexpressed in cancer cells." (PMID 26066322, 2015). "By binding VEGF-A to NRP1, GIPC1 mediates the interaction between NRP1 and ABL1, which activates tyrosine kinase activity and associates with integrins, leading to induce tumor growth." (PMID 26209534, 2015). "Gene deletion of NRP-1 in macrophages favors TAMs' entrapment in normoxic tumor regions, which abates their proangiogenic and immunosuppressive functions and inhibits tumor growth and metastasis." (PMID 25873749, 2015). "In a preclinical xenograft NSCLC model, administration of a function-blocking anti-NRP1B antibody in order to block VEGF binding to NRP1, resulted in marginal tumor growth delay and additive effects to anti-VEGF therapy in reducing tumor growth." (PMID 25954957, 2015). "Overexpression of NRP1 in prostate carcinoma, colon carcinoma and glioma cancer models induces tumor angiogenesis and promotes tumor progression." (PMID 26030152, 2015). "A number of types of malignant tumor cell express NRP1, and this appears to contribute to tumor cell aggressiveness." (PMID 25954957, 2015). "Our previous study indicated that X-rays can induce NRP1 to upregulate T regulatory cells 13, which play an important role in tumour immunosuppression." (PMID 26147006, 2015). "In particular, the anti-angiogenic microRNA miR-320a, by targeting NRP-1, suppressed the in vitro migration, adhesion and tubule formation by vascular endothelial cells, and reduced in vivo tumor angiogenesis and colon cancer cell migration and invasion." (PMID 26090340, 2015). "NRP1 is known to play role in multiple signaling pathways that promote tumor growth, invasion and metastasis." (PMID 26097868, 2015). "NRP-1 has been indicated as a promoter of epithelial-mesenchymal transition, a critical step in tumor invasion and disease progression." (PMID 26090340, 2015). "NRP1 is over-expressed in angiogenic vessels in 98–100% of carcinomas, and plays a vascular-specific role in tumor-mediated angiogenesis." (PMID 26398657, 2015). "qRT-PCR and Western blot assays indicated that the expression levels of NRP1 mRNA and protein were significantly lower in tumours from shNRP1-A549 cells than in tumours from A549 cells." (PMID 26147006, 2015). "NRP-1 has been shown to be the target of several microRNAs (miR), such as miR-9, miR-181b, and miR-320, which modulate angiogenesis and tumor invasion." (PMID 26090340, 2015). "NRP-1 protein is upregulated on tumor-infiltrating lymphocytes (TILs) and can be induced on peripheral blood mononuclear cells by tumor tissue." (PMID 25873749, 2015). "To confirm the expression of ανβ3, ανβ5 and NRP-1 in tumor tissue, we developed a BALB/c nude mouse xenograft model with the human NSCLC cell line A549." (PMID 26066322, 2015). "Our results showed that ανβ3, ανβ5 and NRP-1, which mediate the tumor-penetration activity of iRGD, were overexpressed in human NSCLC cell line A549 and xenograft established with this cell line." (PMID 26066322, 2015). "sNRP-1, functioning as natural ligand trap, inhibits the interaction of VEGF-A or other growth factors with their specific receptors and with membrane NRP-1 expressed by tumor or normal cells." (PMID 26090340, 2015). "As for its important roles in tumourigenesis and tumour progression, NRP1 has the potential to be a good therapeutic molecular target in cancer therapy." (PMID 26147006, 2015).
tumor (continued). "Increased levels of NRP-1 correlate with tumor aggressiveness, advanced disease stage, and poor prognosis." (PMID 26090340, 2015). "Considerable experimental evidence has shown that NRP1 plays an essential role in tumour growth and metastasis by regulating angiogenesis." (PMID 26147006, 2015). "The activation of NRP-1 increases the permeability of blood vessels and tumor tissues, which allows drugs to penetrate into the internal tissue of the tumor much more easily." (PMID 26066322, 2015). "To date, the expression of NRP1 by tumor cells has been shown to contribute to proliferative signal transduction from VEGF-A." (PMID 26209534, 2015). "In the present study, we showed that VEGF-A promoted tumor cell proliferation via the NRP1 signaling pathway." (PMID 26209534, 2015). "Increased NRP1 expression has been detected in tumor cell lines and tumor biopsies of various origins." (PMID 25954957, 2015). "NRP1 has been shown to act as a co-receptor in multiple signaling pathways that promote tumor growth and progression." (PMID 26097868, 2015). "The content of NRP-1 in the tumor tissues (308787.75±27988.79) was significantly lower than that of the peritumoral tissue (726480.76±22573.14; p < 0.001)." (PMID 25333267, 2014). "Neuropilin-1 (NRP1) is a co-receptor for vascular endothelial growth factor (VEGF), and hence is associated with angiogenesis and tumor growth." (PMID 24708840, 2014). "The impetus for using Nrp1 antibody blockade in cancer derives from its direct role in tumor cell survival and proliferation, its role in VEGF ligand-mediated angiogenesis, and also in the augmentation of Treg suppression." (PMID 25343644, 2014). "In vivo, we found that tumor growth was significantly inhibited by the forced expression of miR-338 but was restored by NRP1 overexpression." (PMID 24736504, 2014). "Data from 2 representative patients clearly demonstrates less proliferation from Nrp-1+ tumor-infiltrating CD8+ T cells relative to Nrp1-negative T cells isolated from PBL." (PMID 25343644, 2014). "Immunohistochemical analysis of NRP1 in OSCC tissue samples further supported a key mediator role for NRP1 in tumor progression, lymph node metastasis, and indicated that NRP1 is a predictor for poor prognosis in OSCC patients." (PMID 24999732, 2014). "In tumor cells, ligation of Nrp1 can either promote cell survival or induce apoptosis, depending on the specific co-receptor and ligand involved." (PMID 25343644, 2014). "We found that the expression levels of fibronectin, vimentin, N-cadherin and SNAIL were decreased but the expression of E-cadherin was increased in the NRP1-depleted tumor cells." (PMID 24736504, 2014). "We also observed a similar Nrp1 expression profile on human tumor infiltrating CD4+ and CD8+ T cells." (PMID 25343644, 2014). "Among the 90 samples, positive staining for NRP1 was observed in all of the tumor specimens, while only 6 cases were positive for NRP1 expression among the 30 normal oral epithelial tissues evaluated." (PMID 24999732, 2014). "We found that the mRNA transcript levels of NRP-1 were −11.6±0.25 in the tumor tissues and −2.3±0.15 in the peritumoral liver tissues (p < 0.001)." (PMID 25333267, 2014). "Research has shown that NRP1 is up-regulated in multiple tumor types and is expressed in different tumor vasculatures, suggesting that NRP1 plays a critical role in tumor progression." (PMID 24736504, 2014). "Expression of Nrp1 has been described on a variety of human tumor cells, tumor infiltrating Tregs, and peripheral blood lymphocytes." (PMID 25343644, 2014). "In our study, NRP1 expression was reduced by miR-338 in tumor cells and reduced NRP1 expression attenuate the xenografted tumor D-MVA." (PMID 24736504, 2014). "NRP1 encodes a receptor for VEGF and a block to NRP1 suppresses tumor growth due to decreased angiogenesis and cell proliferation." (PMID 24977165, 2014).